HIF1A (hypoxia inducible factor 1 subunit alpha)
Diseases named in the same sentence as HIF1A in open-access papers (continued):
Sharing a sentence is not in itself a finding about the gene and the disease.
diabetes (247 papers, 2009 to 2026). "HIF-1α, as a key transcription factor, is involved in regulating multiple biological processes associated with diabetes, including but not limited to glucose metabolism, lipid metabolism, angiogenesis, apoptosis, and inflammatory responses." (PMID 40143173, 2025). "In the STZ-diabetes model, combined multikinase inhibition alongside insulin administration was associated with suppression of HIF1α and VEGF in the retina and preservation of retinal architecture compared with diabetic controls." (PMID 41169477, 2025). "Maternal diabetes and Hif1a mutation significantly reduced TH+ and TUJ1+ cardiac innervation when compared to hearts from non-diabetic pregnancies and control hearts, respectively." (PMID 38505753, 2024). "In the mouse model, we performed a comprehensive analysis of the combined impact of a Hif1a-deficient sympathetic system and the maternal diabetes environment on both heart development and the formation of the cardiac sympathetic system." (PMID 38505753, 2024). "In this study, we present a comprehensive analysis of the combined impact of the Hif1a-deficient cardiac sympathetic system and the adverse maternal diabetes environment on embryonal development." (PMID 38505753, 2024). "Excessive oxygen consumption brought on by diabetes-related metabolic changes causes renal tissue hypoxia and increased expression of HIF-1α; the crucial transcriptional regulator of cellular accommodation with hypoxia." (PMID 39033184, 2024). "The mutation and abnormal expression of HIF-1α are related to the occurrence and development of many diseases, such as tumors, cardiovascular disease, and diabetes." (PMID 39199933, 2024). "This study measured serum hypoxia--inducible factor-1 (HIF-1α) andsurvivin levels in patients with diabetes and investigated their associationwith the severity of retinopathy." (PMID 38656026, 2024). "It is a crucial player of the WNT signalling and is known to interact with transcriptionfactor7like2(TCF7L2),ForkheadboxproteinO(FOXO), and HIF1A, and previously implicated in the diabetes-cancer link." (PMID 39281650, 2024). "Our previous studies have demonstrated that defective hypoxic signaling and the loss of HIF-1α expression contribute to impaired angiogenesis and cardiac dysfunction in diabetes." (PMID 37048134, 2023). "In previous studies, in chronic hypoxia-induced diabetes models caused by renal ischemia, HIF-1α and HO-1 levels were found to be increased in the kidney, accompanied by oxidative stress and lipid peroxidation." (PMID 38111578, 2023). "In the present study, using the same model, we report that Hif1a deficiency in sympathetic neurons in combination with diabetes resulted in worsened cardiac function, accelerated adverse structural remodeling and sympathetic denervation in the heart." (PMID 37072781, 2023). "Longitudinal exposure of Hif1aCKO mice to diabetes, spanning 2 months, revealed that the combination of diabetes and Hif1a deficiency in the sympathetic nervous system resulted in compromised cardiac performance and accelerated adverse myocardial remodeling." (PMID 37072781, 2023). "Diabetes was associated with abnormally elevated serum levels of the main mediator of adaptive response to hypoxia (HIF-1α), which develops in a hyperglycaemic environment that impairs its transcriptional activity." (PMID 37686781, 2023). "We focused on the early phase of diabetes-exposure to uncover the effects of the Hif1a-deficient sympathetic system on functional and structural adaptations of the diabetic heart." (PMID 37072781, 2023). "To characterize the impact of diabetes and Hif1a deficiency, we analyzed potential changes in secretion of epinephrine by measuring epinephrine levels in plasma of non-diabetic and diabetic, control and Hif1aCKO mice." (PMID 37072781, 2023).
diabetes (continued). "We employed an early phase of diabetes-exposure model to investigate the effects of the Hif1a-deficient sympathetic system on functional and structural adaptations of the diabetic heart." (PMID 37072781, 2023). "We provide evidence that the combination of diabetes and the Hif1a deficient sympathetic nervous system results in compromised cardiac performance and accelerated adverse myocardial remodeling, associated with the progression of diabetic cardiomyopathy." (PMID 37072781, 2023). "In diabetic tissues, hypoxia triggered by insufficient activation of HIF-1α signaling and impaired adaptive responses to hypoxia are fundamental pathogenic factors during the development of diabetes and diabetic complications." (PMID 35684364, 2022). "HIF-1α expression is accompanied by renal fibrosis in diabetes, and HIF-1α upregulation can cause renal injury." (PMID 35721758, 2022). "The current study showed a significant association of HIF-1α rs11549465 SNP with NPDR progression among T2DM patients who have suffered from diabetes for 12 years." (PMID 35969320, 2022). "In summary, we demonstrate here that the spike protein subunit 1 from SARS-CoV-2 causes activation of HIF-1α dependent glycolysis and inflammatory cytokine production in monocytes which can be suppressed by treatment with the diabetes drug metformin." (PMID 34858397, 2021). "The authors concluded that HIF1A deficiency and maternal diabetes exposure increase the predisposition to cardiac dysfunction in offspring." (PMID 34946940, 2021). "The HIF-1A Pro582Ser polymorphism is also protective against the occurrence of diabetes in the Japanese population." (PMID 33496820, 2021). "The combination of diabetic pregnancy and HIF1A deficiency changes vascular homeostasis in the myocardium due to maternal diabetes and increases the risk of cardiovascular abnormalities in offspring." (PMID 34521346, 2021). "Diabetes-associated retinal ischemia and hypoxia increase the expression of HIF-1α, which leads to increased expression of vascular endothelial growth factor (VEGF), a potent mediator of vascular permeability and neovascularization." (PMID 35002773, 2021). "A C → T non-synonymous single nucleotide polymorphism of HIF-1α gene has been indicated to having a protective effect against diabetes in the Japanese and Hungarian population." (PMID 34209501, 2021). "Summary of meta-analysis of association of HIF1A Pro582Ser (rs11549465) genetic polymorphism with risk of diabetes and diabetic complications." (PMID 32658866, 2020). "As an example, human single-nucleotide polymorphism at the exon 12 (P582S) of HIF1-α was recurrent in Japanese patients with Type 2 diabetes mellitus." (PMID 32816039, 2020). "What's more, the meta-analysis based on the corrected ORs also revealed that the HIF1A Pro582Ser polymorphism played a protective role in the risk of diabetes and diabetic complications." (PMID 32658866, 2020). "Characteristics of the included studies of association of HIF1A Pro582Ser (rs11549465) and Ala588Thr (rs11549467) genetic polymorphisms with diabetes and diabetic complications." (PMID 32658866, 2020). "Taken together, these findings revealed the protective effect of HIF1A Pro582Ser polymorphism against diabetes and diabetic complications." (PMID 32658866, 2020). "The results indicated HIF1A Pro582Ser polymorphism was significantly associated with reduced risk of diabetes under the heterozygous genetic model." (PMID 32658866, 2020). "Summary of meta-analysis of association of the HIF1A Ala588Thr (rs11549465) genetic polymorphism with risk of diabetes and diabetic complications." (PMID 32658866, 2020).
diabetes (continued). "In both humans and rodents, obesity-induced diabetes is associated with hypoxia in tissues such adipose tissue, and suppression of HIF-1α mitigates tissue-specific pathological changes associated with HFD." (PMID 32085589, 2020). "Hyperglycemia increases HIF-1α accumulation and disrupts HIF-1α stability that causes cellular damage in diabetes via several mechanisms." (PMID 33202982, 2020). "There was a protective association between HIF1A Pro582Ser polymorphism and diabetes under the heterozygous genetic model (OR = 0.70, 95% CI = 0.55-0.91; P = 0.007)." (PMID 32658866, 2020). "Several other studies also focused on the associations of HIF1A Pro582Ser and Ala588Thr polymorphisms with diabetes and diabetic complications, including type 1 and type 2 diabetes, diabetic nephropathy, diabetic retinopathy and diabetic foot ulcers." (PMID 32658866, 2020). "HIF-1 signaling pathway: Inhibition of HIF-1 signaling caused by diabetes is associated with hypoxia and high degradation of HIF-1α protein." (PMID 33382706, 2020). "Summary of meta-analysis of association of the HIF1A Pro582Ser (rs11549465) genetic polymorphism with risk of diabetes and diabetic complications after omitting the outlier." (PMID 32658866, 2020). "It has been postulated that the function of HIF-1a is repressed by hyperglycemia leading to the loss of cellular adaptation to hypoxia in diabetes, which suggests a mechanism in the pathophysiology of diabetes and diabetic complications." (PMID 32658866, 2020). "In contrast, for the meta-analysis of the HIF1A Pro582Ser polymorphism in the risk of diabetes, significant heterogeneity was found in all genetic models except the heterozygous genetic model." (PMID 32658866, 2020). "In conclusion, our meta-analysis revealed the protective role of the HIF1A Pro582Ser polymorphism against diabetes and diabetic complications." (PMID 32658866, 2020). "The HIF-1A Pro582Ser polymorphism has been shown to be more active in diabetes, due to a relative resistance to the hyperglycemia-induced repression of HIF-1α transactivation activity." (PMID 31214621, 2019). "We identified a protective effect of HIF-1A Pro582Ser against developing severe DR with a risk reduction of 95%, even when adjusting for known risk factors for DR such as diabetes duration, hyperglycemia, and hypertension." (PMID 31214621, 2019). "Altogether, our data suggest metabolic cardiac remodelling associated with Hif1a deficiency and maternal diabetes exposure." (PMID 29753320, 2018). "HIF-1α is destabilized by hyperglycemia leading to the loss of cellular adaptation to low oxygen in diabetes." (PMID 29753320, 2018). "Transcriptional profiling by RNA-seq revealed significant transcriptome changes in the left ventricle of diabetes-exposed Hif1a+/− offspring associated with development, metabolism, apoptosis, and blood vessel physiology." (PMID 29753320, 2018). "The combination of Hif1α deficiency and diabetes resulted in an altered transcriptional expression profile of the renal cortex and decreased survival of podocytes." (PMID 28774305, 2017). "Together with the increased expression Nphs2, a marker for podocyte damage, our data thus indicate that Hif1α partial deficiency combined with diabetes accelerates podocyte loss and the inability to sustain the glomerular filtration barrier." (PMID 28774305, 2017). "Six weeks after diabetes-induction, Hif1α deficient mice showed more prominent changes in biochemical serum parameters associated with glomerular injury, increased expression of podocyte damage markers, and loss of podocytes compared to wild-type mice." (PMID 28774305, 2017). "In conjunction with these studies, our data demonstrate that a partial Hif1α deficiency promotes the diabetes-induced kidney injury." (PMID 28774305, 2017). "We used a streptozotocin-induced diabetes mouse model and compared biochemical, histological and molecular parameters associated with kidney damage in Hif1α deficient (Hif1α+/-) and wild-type mice." (PMID 28774305, 2017).
diabetes (continued). "Diabetes-associated dysfunction in angiogenesis predominantly contributes to impairment of wound closure, but a role of hypoxia-inducible factor 1 alpha (HIF-1a) in the process remain poorly understood." (PMID 29371983, 2017). "This study assesses the effects of partial Hif1α+/− deficiency on the progression of DN in early stages of diabetes." (PMID 28774305, 2017). "It suggests that Hif1a+/- deficiency promotes the development of systolic dysfunction in the diabetes-exposed heart." (PMID 24502509, 2014). "Diabetes is a major risk factor of cardiovascular disease, HIF-1α has also been shown to be closely associated with it." (PMID 24564828, 2014). "The combination effects of the partial deficiency of Hif1a and diabetes affected the gene expression profile of the heart, including reduced vascular endothelial growth factor A (Vegfa) expression." (PMID 24502509, 2014). "For the first time, we showed that the partial deficiency of Hif1a accelerated the early-phase pathological effects of diabetes on the heart." (PMID 24502509, 2014). "We detected a reduction in the gap-junctional phosphorylated form of Cx43 in the LV of the Hif1a+/- diabetic heart, which has been associated with diabetes-induced structural remodeling and impaired ventricular contractions." (PMID 24502509, 2014). "In clinical practice, the presence of these polymorphisms is associated with the development of diseases such as cancer, diabetes, and coronary disease, in which an altered HIF-1α is observed in various groups among different populations." (PMID 23991178, 2013). "Hyperglycemia was shown to be involved in the loss of cell response to hypoxia in diabetes, through a mechanism that is likely to involve downregulation of HIF-1α." (PMID 21124777, 2010). "The main goal of our analysis was to study the association between the HIF-1α gene polymorphism and diabetes." (PMID 19691832, 2009). "While HIF-1α targeting in EC is widely recognized and linked with improved overall survival, its depletion in EC patients with diabetes might impact mortality related to diabetic complications, posing an additional health challenge." (PMID 39996906, 2025). "HIF-1α deficient mice with induced diabetes also displayed decreased body weight, increased fasting blood glucose, urinary albumin, and systolic blood pressure compared to a diabetic mouse model with HIF-1α expression." (PMID 39648258, 2025). "It provides the first comprehensive analysis of how maternal diabetes exposure affects the development of the cardiac sympathetic system, highlighting the combined impact of the Hif1a-deficient sympathetic system and the maternal diabetes environment on the heart." (PMID 38505753, 2024). "This study investigates the combined impact of the Hif1a-deficient sympathetic system and maternal diabetes on heart development, specifically focusing on cardiac innervation, coronary artery formation, and the development of postganglionic sympathetic neurons of the cardiac sympathetic system." (PMID 38505753, 2024). "Furthermore, diabetic Hif1aCKO animals showed significantly larger collagen accumulation compared to diabetic control hearts, indicating a synergistic effect of Hif1a-deficient sympathetic system and diabetes on collagen deposition." (PMID 37072781, 2023). "Furthermore, genetic association studies indicate an association between polymorphisms in the HIF-1α gene and human diabetes." (PMID 37189396, 2023). "HIF-1α deficiency may accelerate renal injury in the early stage of streptozotocin-induced diabetes in mice." (PMID 36297636, 2022). "In addition, HIF-1α is also associated with the development of microvascular and macrovascular complications in diabetes." (PMID 35684364, 2022). "Finally, based on the study inclusion criteria, 8 articles involving 11 eligible studies for the association of HIF1A Pro582Ser and Ala588Thr polymorphisms with diabetes and diabetic complications were included in our meta-analysis." (PMID 32658866, 2020).
diabetes (continued). "Previous studies indicated that HIF1A Pro582Ser and Ala588Thr may be associated with diabetes and diabetic complications." (PMID 32658866, 2020). "In addition, due to the small number of studies included in the meta-analysis of HIF1A Ala588Thr polymorphism with the risk of diabetes and its complications, the findings should be interpreted with caution." (PMID 32658866, 2020). "For example, vascular endothelial growth factor, another susceptibility gene for diabetes, may interact with HIF1A gene." (PMID 32658866, 2020). "The results show that diabetes not only causes hypoxia but also affects HIF-1α signaling." (PMID 33692685, 2020). "Several studies indicated that hypoxia-inducible factor 1-alpha (HIF1A) genetic polymorphisms may be associated with diabetes and diabetic complications." (PMID 32658866, 2020). "Furthermore, the presence of the non-synonymous single-nucleotide polymorphism (rs11549465) in HIF-1α gene in the Japanese and Hungarian populations reduced the risk of developing diabetes." (PMID 33013447, 2020). "Clarifying the molecular regulatory mechanisms underlying HIF-1α expression by SGLT2 inhibitors could lead to the improvement to manage diabetes and other diabetic complications and comorbidities." (PMID 31611596, 2019). "In a mouse model of maternal diabetes exposure, HIF-1α heterozygous loss-of-function was associated with impaired cardiac function and structural reprogramming of the heart of offspring, including decreased macrophage migration, increased accumulation of AGEs, and altered Vegfa expression." (PMID 29753320, 2018). "To provide more insight into the functional role of HIF-1α pathways, we examine the relationship between diabetes-induced kidney injury and the partial deficiency of HIF-1α caused by the global deletion of the Hif1α functional allele with a specific focus on the early phase of diabetes-exposure." (PMID 28774305, 2017). "Angiopathies induced by diabetes, including thrombus and infarction, may cause blood and oxygen deficiency in the whole body, resulting in the upregulation of HIF-1α." (PMID 25371752, 2014). "Previous studies have suggested that metformin may improve oxygenation and suppress the accumulation of HIF-1α in diseases associated with tumors or diabetes through the activation of the AMPK/mTOR pathway and the repression of oxygen consumption." (PMID 25310259, 2014). "Our results provide evidence that HIF-1α regulates early cardiac responses to diabetes, and that HIF-1α deregulation may influence the increased risk for diabetic cardiomyopathy." (PMID 24502509, 2014). "Nevertheless, the blockade of neovasculization by PCE may be attributed to its inhibition of HIF-1α induction caused by diabetes-associated microvascular hypoxia of glomeruli mildly injured in the early stage of DN." (PMID 24278186, 2013). "Furthermore, in various groups among different populations, an association has been found between the presence of these polymorphisms and the development of diseases in which an altered HIF-1α is implicated, such as cancer, diabetes and coronary disease." (PMID 21414224, 2011). "However, in certain contexts, HIF-1α upregulation has been linked to diabetes-associated complications, suggesting that the regulation of HIF-1α may have a dual role in diabetes-related reproductive health issues." (PMID 40867634, 2025). "Furthermore, HIF-1α may help stabilize androgen levels by preserving Leydig cell function, potentially alleviating diabetes-associated gonadal dysfunction." (PMID 40867634, 2025). "Consequently, the combination of diabetes and Hif1a-deficient sympathetic system exacerbates adverse cardiac remodeling, demonstrated by the escalated accumulation of AGEs and collagens, macrophage infiltration, and increased expression of cardiac injury markers." (PMID 37072781, 2023).